TNF (tumor necrosis factor)
Diseases named in the same sentence as TNF in open-access papers (continued):
Sharing a sentence is not in itself a finding about the gene and the disease.
periodontal disease (continued). "Although it is documented that TNF promotes bone resorption and periodontal disease progression via TNFR1, the non-selective inhibition of TNFR might block additional inflammatory pathways that contribute to the efficacy seen in observational studies." (PMID 36845132, 2023). "Periodontal disease was successfully induced in rats using the ligature technique on the lower incisors, as confirmed by clinical parameters and the increase in salivary MMP-8 levels and plasma levels of IL-1 and TNF-α, regarded as biomarkers of periodontal disease." (PMID 36840029, 2023). "Moreover, a negative correlation between miR-23a-3p and TNFα (r = -0.891, p < 0.01) and IL-6 (r = − 0.503, p < 0.05) was observed in the early stage of periodontal disease." (PMID 36599866, 2023). "Thus, the pathological roles of TNF-α and IL-8 in periodontal disease in HD patients are not fully understood." (PMID 31382656, 2019). "Significantly increased concentrations of inflammatory mediators of IL-1β, IL-6, TNF-α and β-glucuronidase in saliva and IL-1β, β-glucuronidase and TNF-α in serum were found among pre-conception women with moderate/severe periodontal disease, compared with women without periodontal disease." (PMID 27978823, 2016). "The number of sextants without signs of periodontal disease (CPI 0) was correlated negatively with fibrinogen (r = −0.272; p < 0.05) and TNF-α (r = −0.233; p < 0.05) levels." (PMID 36769794, 2023). "Although differences in TNF-α and TNF-β were not correlated with the periodontal disease treatment outcome, differences in IL-1α, IL-1β, IL-6, and IL-8 were significantly higher in the ET group in this study." (PMID 25884025, 2015).
endometriosis (357 papers, 2005 to 2026). The growth of functional endometrial tissue in anatomic sites outside the uterine body. "Inflammatory processes associated with endometriosis lead to elevated levels of pro-inflammatory cytokines, such as IL-6 and TNF-α, as well as increased oxidative stress." (PMID 40564779, 2025). "Dysregulation of the TNF-α pathway has been linked to conditions like uterine fibroids and endometriosis, potentially inducing apoptosis and cell dissociation in the endometrium, leading to menstrual shedding and heavy bleeding." (PMID 40028534, 2025). "The anti-inflammatory effects of diets high in ω-3 PUFAs, which are achieved by reducing TNF-α and IL-6 levels, contribute to lowering the risk of endometriosis among women." (PMID 40313408, 2025). "Follicular fluids from endometriosis patients contain higher levels of inflammatory cytokines (IL-1β, IL-6, IL-8, TNF-α, MCP-1), suggesting that endometriomas cause inflammatory changes to surrounding follicles." (PMID 40679648, 2025). "Immunological Impact: Research on animals demonstrates that antibiotic treatment lowers levels of important inflammatory cytokines, including IL-1β, IL-6, and TNF-α, which are associated with endometriosis development." (PMID 40725782, 2025). "A meta-analysis of 42 studies including 5414 women show significant associations between some variants of TNF-α gene polymorphisms and increased risk of endometriosis in Asian and Chinese populations." (PMID 40507929, 2025). "The association between TNF-α gene polymorphism and risk of endometriosis has also been shown in the Greek population." (PMID 40507929, 2025). "It is associated with increased levels of IL-6, TNF-alpha, and IL-1 beta, representing another pathogenic mechanism associated with the development of endometriosis." (PMID 38337827, 2024). "Increased levels of TNF-α and glycodelin were associated with hyperexcitability to electrical stimulation and severe menstrual pain in women with endometriosis." (PMID 37893241, 2023). "TNF-α is a proinflammatory cytokine, and, while its function in BM is controversial, it has been clearly implicated in the pathophysiology of endometriosis." (PMID 37545483, 2023). "Promising results of treating endometriosis-associated infertility with TNF-α blockers supports our findings." (PMID 37020589, 2023). "In the current study, we examined the ability of TNFα to induce dysregulation of microRNAs (miRNAs) linked to NFkB-signaling pathways, thus contributing to the pathogenesis of endometriosis." (PMID 37205467, 2023). "Studies have demonstrated that several cytokines are associated with the evolution of endometriosis, including tumor necrosis factor-α (TNFα)." (PMID 37205467, 2023). "In patients with endometriosis, the upregulation of miRNA 125b-5p and downregulation of let 7b-5p have been associated with increased proinflammatory cytokines such as TNF-α, IL-1β, and IL-6." (PMID 37834449, 2023). "Similar to the previous experiments with estradiol, we analyzed ESCs after treatment with TNF-α and IL-1β, the representative cytokines associated with endometriosis, alone and in combination with DNG." (PMID 36428561, 2022). "SR-16234 can suppress the expression of genes associated with inflammation in endometriosis-like lesions, such as TNF-α and IL-1β, preventing the growth and proliferation of endometriotic tissues." (PMID 35885010, 2022). "In this context, infliximab, an anti-TNFα monoclonal antibody, has been applied to treat endometriosis and relieve endometriosis-associated pain." (PMID 36358904, 2022). "Increased expression of BIRC2, BIRC3, BIRC4, and BIRC5 is associated with endometriosis, and tumor necrosis factor-α increases BIRC3 expression in endometrial stromal cells in vitro." (PMID 34530503, 2022). "Positive (− 1031), negative (− 308, − 238) or ambiguous (− 863, − 857) associations have been reported between TNF-α polymorphisms and endometriosis." (PMID 36028805, 2022).
endometriosis (continued). "Tumor necrosis factor alpha (TNF-α) and interleukin 1 beta (IL-1β) are proinflammatory factors that have been associated with the progression of endometriosis." (PMID 36428561, 2022). "The associations analysis suggests an approximate fourfold increased risk for women with endometriosis stage IV with TNF*2-allele heterozygote genotype and an approximate 3.5-fold increased risk with TNF*2-allele." (PMID 36028805, 2022). "Secondary to inflammation associated with endometriosis, the NK cell-mediated release of cytokines and pro-angiogenic factors such as TNF-α and IFN-γ creates an optimal microenvironment for the proliferation of ectopic endometriotic lesions." (PMID 36613776, 2022). "Etanercept, another TNF antagonist, has been shown to have a positive effect on pregnancy rates in patients with endometriosis-associated infertility or ovarian endometrial cysts undergoing IVF treatment." (PMID 34945174, 2021). "Another study investigating plasma inflammatory markers found that elevated plasma levels of IL-1β and TNF-α were associated with increased risk for endometriosis." (PMID 34073257, 2021). "Their data showed an increase of TH1–TH2 ratio caused by the increased amount of TNF-α and IL-2 in women with severe endometriosis." (PMID 34639133, 2021). "In a meta‐analysis study, Cao and coworkers investigated the association of TNF‐α gene T‐1031C polymorphism with endometriosis." (PMID 34557653, 2021). "It is known that TNF-α is a major proinflammatory cytokine that has been implicated in endometriosis pathogenesis." (PMID 34616540, 2021). "Overexpression of Sema3C, Sema3F, and TNF will induce the loss of sympathetic nerve fibers in endometriosis." (PMID 32145751, 2020). "Endometriosis is an inflammatory disease caused by increased TNF-α and IL-1β, which reduce the protein expression of Bax and increase Bcl-2 to inhibit the apoptosis of endometriotic lesions." (PMID 33266505, 2020). "These endometriosis-like phenotypes can be reproduced in control ME-SFCs by exposure to inflammatory cytokines (TNF and IL-1β) and are associated with increased cell migration." (PMID 36304708, 2020). "TNF-α is significantly increased in the peritoneal fluid of women with endometriosis and has been associated with endometriosis progression and related infertility." (PMID 31831028, 2019). "One of the key pathologic features of endometriosis is inflammation, which is associated with rising levels of proinflammatory cytokines, such as interleukin (IL)-6, IL-8, and tumor necrosis factor (TNF)-α." (PMID 29916217, 2019). "The present study aimed at examining the associationof four TNF-α polymorphisms, -238G/A, -308G/A, -857C/Tand -863C/A with endometriosis in an Iranian sample." (PMID 30644238, 2019). "This study aimed to examine the association of four TNF-α polymor-phisms, namely -238G/A, -308G/A, -857C/T and -863C/A, with susceptibility to endometriosis in an Iranian population." (PMID 30644238, 2019). "Our study reportedan association between the -863C/A polymorphism in thepromoter region of TNF-α and endometriosis." (PMID 30644238, 2019). "There is a strong relationship between the TNF-α gene promoter region -1031T/C polymorphism and endometriosis." (PMID 30402122, 2018). "We review the association between endometriosis and inflammation and the initial promise of anti-tumor necrosis factor therapies based upon experimental evidence, and how and why these studies have not translated to the clinic." (PMID 26949527, 2016). "The TNF-α promoter -1031 T/C polymorphism is associated with decreased risk of endometriosis in an Iranian population." (PMID 26644856, 2015). "For the first time, TNF-α has been recognized in peritoneal fluid of women with endometriosis, which introduced an association between endometriosis and disorders of the immune system." (PMID 26644856, 2015).
endometriosis (continued). "Elevated TNF-α levels in peritoneal fluid have been associated with up-regulated TNF-α production in peritoneal macrophages and peripheral monocytes of women with endometriosis." (PMID 26644856, 2015). "Our data have demonstrated decreased frequency of the -1031T polymorphism in the promoter region of the TNF-α gene in the most severe cases of endometriosis in our studied population." (PMID 26644856, 2015). "The aim of this study was to assess the associations of -1031 T/C, -238 G/A and -308 G/A polymorphisms in the TNF-α gene promoter region with endometriosis." (PMID 26644856, 2015). "The results of a recent meta-analysis study implies that TNF-α -1031C is associated with a higher risk of endometriosis in Asian individuals in homozygote comparisons and the recessive genetic model." (PMID 26644856, 2015). "In the Japanese population, TNF-α -1031T/C polymorphism was associated with reduction of endometriosis risk." (PMID 26644856, 2015). "We found a strong association between the -1031 T/C polymorphism in the promoter region of the TNF-α gene with endometriosis (P=0.001)." (PMID 26644856, 2015). "Although studies evaluated the association between TNF-α gene polymorphisms and endometriosis, their results were incompatible." (PMID 26644856, 2015). "Up to now, several association studies were reported that the some of polymorphisms of tumor necrosis factor-α (TNF-α) are related with gynecological diseases including pre-eclampsia, endometriosis." (PMID 21970639, 2011). "In contrast, only -1031(T/C) polymorphism in a TNF-α gene plays a part of endometriosis in Asian populations." (PMID 21970639, 2011). "In the mouse genital tract, infertility associated with endometriosis has been shown to be related to the production of TNF-α." (PMID 18489796, 2008). "Elevated levels of pro-inflammatory cytokines, including ILs and TNF-α, are linked to increased pelvic pain and other symptoms of endometriosis and may also affect brain function, contributing to the development of mood disturbances." (PMID 40075795, 2025). "New therapies, including antioxidants, may partially counteract ectopic endometriosis lesions, whereas steroids and tumor necrosis factor-α antagonists may modulate immune factors associated with endometriosis." (PMID 40228263, 2025). "Polymorphisms in the TNF gene (rs361525, rs1800629, rs1799724, rs1800630, and rs1799964) were evaluated, with the analysis revealing that only the rs1799964 variant was significantly associated with an increased risk of endometriosis." (PMID 39767772, 2024). "Endometriosis shares a common inflammatory pathogenesis with cancers, involving TNF-alpha, IL-1, IL-6, IL-8, and VEGF, associated with retrograde menstruation, iron overload, and the activation of macrophages, triggering aberrant inflammatory signaling and impairing phagocytic potential." (PMID 38337827, 2024). "In addition, the pro-inflammatory cytokines TNF-α and interleukin-6 (IL-6) also contain polymorphisms that have been linked to endometriosis." (PMID 37676242, 2023). "This may be related to the main pathogenesis of endometriosis causing a chronic inflammatory environment with increased levels of proinflammatory cytokines such as IL-1β, IL-6, and tumor necrosis factor-α." (PMID 37629431, 2023). "Besides, elevation of TNF-α in peritoneal fluids is associated with infertility induced by endometriosis." (PMID 37143676, 2023). "The evolution of endometriosis has been linked to a range of M1 macrophage polarization markers, including tumor necrosis factor α (TNF-α)—a marker with a strong inflammatory, cytotoxic and angiogenic potential, and IL-1β, IL-12, IL-8, IL-10 and IL-6, which promote the growth of endometrial cells." (PMID 34449536, 2021). "Interestingly, ghrelin levels were not correlated with inflammatory cytokines classically associated with endometriosis, such as interleukin (IL-1β) 1β, IL-6, and tumor necrosis factor (TNF)." (PMID 33986637, 2021).
endometriosis (continued). "It is possible, however, that expression of this chemokine by endometriotic stromal and epithelial cells may be induced and increased by proinflammatory cytokines involved in endometriosis-associated inflammation, e.g., IL-1b, TNF, and IL-17." (PMID 34501240, 2021). "The severity of endometriosis has also been associated with elevated serum TNF-α levels." (PMID 32143439, 2020). "Thus far, some polymorphisms inthe promoter region of the TNF-α gene have been examinedin patients with endometriosis." (PMID 30644238, 2019). "Therefore, for thefirst time, we aimed to examine the relationship of TNF-α-238G/A, -308G/A, -857C/T and -863C/A polymorphismswith risk of developing endometriosis in Iranian women." (PMID 30644238, 2019). "In theory danazol treatment could also cause lowering of TNFα levels as it has been found in endometriosis both in vitro and in vivo." (PMID 30885236, 2019). "All in all, endometriosis has been reported to be linkedwith a number of polymorphisms of TNF-α." (PMID 30644238, 2019). "Koninckxet al. analyzed the role of TNF-alpha in pelvic inflammation and pain associated with endometriosis, and verified if these ailments may be attenuated with anti-TNF monoclonal antibodies." (PMID 28376925, 2017). "In addition, anti-TNF therapy is an essential part of endometriosis treatment and an association between TNF-α gene polymorphisms with endometriosis has been reported in in several ethnic populations." (PMID 26644856, 2015). "In this study, an association was demonstrated between the -1031C/T TNF-α polymorphism and endometriosis, which indicated that it could be used as a relevant molecular marker to assess the risk of endometriosis." (PMID 26644856, 2015). "A number of studies assessed different TNF-α polymorphisms in endometriosis patients." (PMID 26644856, 2015). "In order to describe the importance of the TNF-α -1031T/C polymorphism, additional research would be necessary to clarify the relationship between this multi-functional proinflammatory cytokine with endometriosis." (PMID 26644856, 2015). "However in another study the TNF-α -1031T/C polymorphism has shown a relation with endometriosis in the Iranian population." (PMID 26644856, 2015). "In addition, endometriosis patients showed high concentrations of TNFα in ovarian follicular fluids, which is associated with poor oocyte quality or impaired fertilization." (PMID 25331066, 2014). "Moreover, an Indian population study suggests an association between TNFα-C850T polymorphism and endometriosis." (PMID 23843796, 2013). "Furthermore, danazol inhibits the production of IL-1 and TNF by monocytes in a dose-dependent manner and inhibits the cytotoxicity of macrophage/monocyte-mediated susceptible target cells in patients with mild endometriosis." (PMID 37138868, 2023). "For example, in endometriosis, an excess of pro-inflammatory cytokines such as TNF-α and IL-6 contributes to chronic inflammation and tissue damage, disrupting the normal function of the reproductive organs." (PMID 41377340, 2025). "A study conducted on women with endometriosis found elevated levels of the inflammatory proteins interleukin IL‐6, IL‐8, and TNF‐α in their peritoneal fluid, indicating their potential contribution to the inflammatory processes associated with the condition." (PMID 39803270, 2025). "NLRC5 levels are higher in the ectopic and eutopic endometria of endometriosis patients compared to those with leiomyoma, peaking in the ectopic endometrium, and it suppresses IL-6 and TNF-α." (PMID 40508002, 2025). "Women with endometriosis have elevated levels of key pro-inflammatory cytokines, i.e., IL-1β, IL-6, and TNF-α." (PMID 39859551, 2025). "Proteomic and metabolomic analyses are further advancing this field, identifying inflammatory markers such as IL-6 and TNF-α as well as altered metabolic profiles in endometriosis patients." (PMID 40075795, 2025).